BAX (BCL2 associated X, apoptosis regulator)
Diseases named in the same sentence as BAX in open-access papers (continued):
Sharing a sentence is not in itself a finding about the gene and the disease.
schizophrenia (3 papers, 2012 to 2026). A major psychotic disorder characterized by abnormalities in the perception or expression of reality. "The networks we built for schizophrenia risk miRNAs imply the disease-associated deregulation of BCL2/BAX and the resultant enhancement in cell susceptibility to apoptosis, which possibly involves an increase in the production of reactive oxygen species." (PMID 32194626, 2020). "The increased levels of the anti-apoptotic/pro–cell survival markers MCL1 and BCL2 and unchanged levels of the pro–cell death markers BID and BAX suggest a balance toward activated cell survival mechanisms in the midbrains of individuals with schizophrenia and bipolar disorder." (PMID 41567988, 2026). "Furthermore, an increased ratio of pro-apoptotic BAX to anti-apoptotic BCL-2 protein in the dorsolateral prefrontal cortex (DLPFC) from patients compared with controls suggests a bias favoring cell death processes in schizophrenia." (PMID 22545112, 2012). "Increased protein and mRNA levels of BAX relative to BCL2 have been found in the temporal cortex and PFC of patients with schizophrenia." (PMID 41567988, 2026). "Conversely, other TNFSF downstream mRNAs were unchanged (BAX, BID, CASP1, CASP3, CASP8, and CASP9) in high-inflammation schizophrenia cases compared with low-inflammation controls." (PMID 41567988, 2026). "Although CASP3 activation is a widely used marker indicative of cell death in neurodegenerative disorders, activation of the intrinsic proapoptotic marker BAX in the absence of CASP3 activation has been found in the temporal cortex of people with schizophrenia." (PMID 41567988, 2026).
T cell lymphoma (3 papers, 2017 to 2024). "As T cell lymphoma is a more aggressive disease, the higher Bcl-2/BAX ratio indicates resistance to apoptosis." (PMID 31676831, 2019).
tuberculosis (3 papers, 2018 to 2021). A chronic, recurrent infection caused by the bacterium Mycobacterium tuberculosis. "NBXH upregulates Mapk14 expression, regulates the immune response during M. tuberculosis infection, induces BAX translocation and apoptosis, enhances TNF expression, limits M. tuberculosis, and exerts an anti-TB effect." (PMID 34074345, 2021).
Type 1 diabetes (3 papers, 2020 to 2025).
ulcer (3 papers, 2013 to 2025). "Furthermore, upregulation of BAX in ulcer control group was observed when compared to the mushroom-extract-treated groups." (PMID 24302966, 2013). "By reducing the expression of pro-apoptotic proteins like BAX and increasing anti-apoptotic proteins like BCL-2, HDZJF likely helps to prevent cell death in the oral mucosa, promoting tissue regeneration and reducing ulcer severity." (PMID 40129983, 2025).
astroblastoma (2 papers, 2025).
atrial fibrillation (2 papers, 2013 to 2026). A disorder characterized by an electrocardiographic finding of a supraventricular arrhythmia characterized by the replacement of consistent P waves by rapid oscillations or fibrillatory waves that vary in size, shape and timing and are accompanied by an irregular ventricular response. "This study investigated the effects of high-intensity interval training (HIIT) and moderate aerobic training (AT) on FGF23, Klotho, mineral metabolism, apoptosis markers (BAX, Bcl2), and atrial fibrillation (AF) in a rat CKD model." (PMID 42072635, 2026). "We measured heart weight, blood levels of FGF23, Klotho, and mineral metabolism markers, as well as the heart expression of apoptosis proteins (i.e., BAX, Bcl2) and atrial fibrillation (AF)." (PMID 42072635, 2026).
bladder tumor (2 papers, 2005 to 2022). "This present work is a continuation of the previous published work where thirty bladder tumors were analyzed for the presence of MSI at BAT-26, BAT-40, TGFβ RII, IGFIIR, hMSH3 and BAX." (PMID 15647110, 2005).
brain tumor (2 papers, 2022 to 2023). "Further, the protein expression of BCL2 and BAX in brain tumors of GL261-Vector-bearing or GL261-LRIG3-bearing mice were detected." (PMID 36639372, 2023).
cataract (2 papers, 2022 to 2025). Partial or complete opacity of the crystalline lens of one or both eyes that decreases visual acuity and eventually results in blindness. "Consistent with prior research highlighting the strong association between apoptosis and cataract disease, our findings also revealed a significant increase in ASC mice in the protein levels of apoptotic markers Bcl-2-associated X (BAX) and caspase 3 (CASP3)." (PMID 40641526, 2025). "P. densiflora bark inhibited apoptosis by downregulating mRNA expression levels of caspase 3 and BAX in SD rat pups with selenite-induced cataracts." (PMID 36039041, 2022).
cholangiocarcinoma (2 papers, 2013 to 2015). A carcinoma that arises from the intrahepatic biliary tree (intrahepatic cholangiocarcinoma) or from the junction, or adjacent to the junction, of the right and left hepatic ducts (hilar cholangiocarcinoma). "Furthermore, in cholangiocarcinoma cells, GX15-070 was shown to be a direct activator of BAX." (PMID 26198850, 2015).
chronic myelogenous leukemia (2 papers, 2016 to 2019). "In summary, curcumin treatment might produce a P73-dependent apoptotic cell death in chronic myelogenous leukemia cells (K562), which was triggered by mitotic catastrophe, due to sustained BAX and survivin expression and impairment of the anti-apoptotic proteins BCL-2 and XIAP." (PMID 27832139, 2016).
coronary artery disease (2 papers, 2019 to 2023). "In this work, we investigated the association of BAX promoter DNA methylation with coronary heart disease (CHD) in Han Chinese." (PMID 30681575, 2019). "The comparisons of BAX methylation between coronary heart disease (CHD) and non-CHD by age∗." (PMID 30681575, 2019).
cutaneous squamous cell carcinoma (2 papers, 2017 to 2019). "Loss of BAX by either RNA interference or highly-expressed miR-365 in cells of cutaneous squamous cell carcinoma (CSCC) enhanced the tumor resistance against apoptosis, while repressing cell proliferation, migration, and invasiveness." (PMID 28556798, 2017).
fibrosis (2 papers, 2017 to 2025). the formation of excess fibrous connective tissue in an organ or tissue in a reparative or reactive process. "Moreover, the 1-D-MT fibrosis mice had lower expression of BAX and cleaved caspase 3 in liver tissues than did the WT fibrosis mice." (PMID 28465467, 2017).
gastric tumor (2 papers, 2023 to 2024). "ORI remarkably inhibits the proliferation of gastric tumor and induces apoptosis by activating caspase pathway through upregulating BAX expression and changing BCL/BAX ratio." (PMID 38726411, 2024).
HCMV infection (2 papers, 2014 to 2021). "Furthermore, HCMV infection suppressed the apoptosis of glioblastoma cells by increasing the expression level of activating transcription factor 5 (ATF5) and the B cell lymphoma/leukemia-2 (Bcl-2)-to-Bcl-2-associated X (BAX) protein ratio." (PMID 33921122, 2021). "HCMV infection promotes the expression of ATF5 and elevates the Bcl-2 to BAX ratio and enhances anti-apoptosis in U87 cells." (PMID 25120656, 2014).
hypothyroidism (2 papers, 2024 to 2025). Abnormally low levels of thyroid hormone. "Hypothyroidism has been demonstrated to modify the expression of genes in the BCL-2 family, inducing apoptosis in the brain by diminishing the levels of the Bcl-2 protein, a cell death preventer, and escalating the levels of the BAX protein, which triggers cell death." (PMID 39513900, 2024).
infarct (2 papers, 2015 to 2024). "In a rat infarction model, upregulation of miR-298 significantly reduced the expression of BAX, cytochrome-c and cleaved caspase-3, reduced myocardial apoptosis and improved infarcted cardiac function." (PMID 38271362, 2024). "This was further shown where BAX/BAK/cyclophilin D triple knockout mice did not appear to exhibit a further reduction in myocardial infarct size when compared to the BAX/BAK double knockout mice." (PMID 25987420, 2015).
insulinoma (2 papers, 2022 to 2025). "BAX is an important pro-apoptotic regulator of apoptosis in the intrinsic pathway and an increase in BAX mRNA in BPA treated cells was detected in murine antral follicles, insulinoma cells and macrophages." (PMID 36387888, 2022).
laryngeal squamous cell carcinoma (2 papers, 2024 to 2026). A squamous cell carcinoma that arises from the larynx. "RBM15‐mediated m6A modification of BAX inhibitor motif containing 6 (TMBIM6) by recruiting IGF2BP3 to promote the progression of laryngeal squamous cell carcinoma." (PMID 40923717, 2026).
Legionella infection (2 papers, 2017 to 2022). "To test whether Legionella infection is influenced by a loss of intrinsic (mitochondrial) apoptosis, we utilized BMDMs deficient in BAK alone, or both BAX and BAK, which has been demonstrated to completely prevent intrinsic apoptotic cell death." (PMID 28261564, 2017).
liver cirrhosis (2 papers, 2019 to 2023). "We measured a significant association between the BAX variant and portal vein invasion (p = 0.014) and between the HNF1A variant and liver cirrhosis (p = 0.032)." (PMID 31570105, 2019).
medulloblastoma (2 papers, 2023 to 2025). A malignant, invasive embryonal neoplasm arising from the cerebellum. "BAX and SMAC were most highly expressed in Group 4 medulloblastoma cell lines compared with the SHH and Group 3 subgroups, while pro-caspase 9 was more highly expressed in the SHH subgroup, compared to Group 4 cell lines." (PMID 37898609, 2023).
metabolic dysfunction-associated steatohepatitis (2 papers, 2024 to 2025). Metabolic dysfunction-associated steatohepatitis (MASH, formerly known as nonalcoholic steatohepatitis or NASH) is a type of fatty liver disease. "Consistently, deleting BAX and BAK in a mouse model of Metabolic Dysfunction Associated Steatohepatitis (MASH) reduced expression of RNA sensors and SASP factors." (PMID 39257994, 2024). "Furthermore, BAX and BAK play a key role in mtRNA leakage during senescence, and their deletion diminishes SASP expression in vitro and in a mouse model of Metabolic Dysfunction-Associated Steatohepatitis (MASH)." (PMID 41398033, 2025).
metastatic melanoma (2 papers, 2011 to 2024). A melanoma that has spread from its primary site to another anatomic site. "Conversely, S213F (found in a metastatic melanoma patient) displays a lower BAX TMD binding ability and a decrease in BCL2/ BAX mitochondrial localization, thereby providing a lower level of protection from cell death." (PMID 38670940, 2024).
metastatic tumors (2 papers, 2013 to 2019). "In particular, BAX mRNA was diminished in advanced-stage (T3 and T4) nasopharyngeal tumors and/or metastatic tumors, accompanied either by a number of positive regional lymph nodes only, or also by infiltration of distal organs." (PMID 23777485, 2013).
mucositis (2 papers, 2018 to 2025). Mucositis is inflammation and damage of the mucous membranes lining the mouth and other parts of the gastrointestinal (GI) tract. "Building on this, we hypothesize that HDZJF may improve radiation-induced mucositis by modulating multiple key molecules, such as EGFR, PI3K, AKT, and downstream targets like NF-κB, BAX, and BCL-2." (PMID 40129983, 2025). "This negative feedback of mucositis included mucosal crypt proliferation, regeneration, and anti-apoptosis, assessed by Ki67, CD44, and BAX IHC staining, respectively." (PMID 29867884, 2018).
neuropathy (2 papers, 2021 to 2024). A disorder affecting the nervous system that manifests with pain, tingling, numbness, and/or muscle weakness. "Specific genes increased in patients withoutlinezolid-associated neuropathy included ATG4C, BAX, and IGF1, while patients onlinezolid who suffered from neuropathy had an increase in AURKB, CASP3, CASP8, CDK1,CDKN1B, CEBPB, NADSYN1, NRF1, GPX7, and SBSN." (PMID 38939039, 2024). "However, a BAX inhibitor may be of clinical use because the knockdown of BAX protected cultured axons from neuropathy." (PMID 33162554, 2021).
non-alcoholic fatty liver disease (2 papers, 2021 to 2025). "BP attenuates the severity of colorectal inflammation and liver injuries caused by exposure to dextran sulfate sodium and mitigates nonalcoholic fatty liver disease via JAK1/STAT3/BAX signaling." (PMID 33971886, 2021).
osteonecrosis (2 papers, 2024 to 2025). A none disease characterized by death of bone tissue due to a lack of blood supply. "The results revealed that the associated genes were involved in the BCL-2/BAX apoptotic pathway and the ROS/JNK/c-Jun signaling pathway, further highlighting the significant role of cell apoptosis in glucocorticoid-induced osteonecrosis of the femoral head." (PMID 38384969, 2024).
ovarian tumor (2 papers, 2001 to 2024).
papillary thyroid cancer (2 papers, 2020 to 2025). "In thyroid papillary carcinoma cells, exosome treatment elevated the expression of miR-205-5p and inhibited apoptosis-related proteins BAX and caspase-3, suggesting that miR-205-5p may promote cancer cell survival." (PMID 40687582, 2025). "This study analyzed the effects of exosomes (EXo) and their cargo, microRNA-205-5p (miR-205-5p), on the expression of key apoptosis-related proteins—BAX, caspase-3, ATF4, and CHOP—in thyroid papillary carcinoma cells." (PMID 40687582, 2025). "In experiments involving thyroid papillary carcinoma cells from NTD patients, exosome treatment significantly increased the expression levels of miR-205-5p and inhibited the expression of apoptosis-related proteins such as BAX and caspase-3." (PMID 40687582, 2025).
periodontitis (2 papers, 2023 to 2026). An acute or chronic inflammatory process that affects the tissues that surround and support the teeth. "It is predicted that PTGS2 and BCL2 are the most important targets of the Asarum–Angelica drug pair for regulating periodontitis, and AKT1, CASP3, BAX, RELA, etc., are also relatively important targets." (PMID 38139216, 2023).
pneumonia (2 papers, 2018 to 2024). An acute, acute and chronic, or chronic inflammation focally or diffusely affecting the lung parenchyma, caused by an infection in one or both of the lungs (by bacteria, viruses, fungi, or mycoplasma.). "The findings of the present study revealed that in the animal model of pneumonia, the level of BCL-2 was significantly reduced, while other apoptotic markers including BAX, CASP-3, and CASP-9 were remarkably increased." (PMID 38580929, 2024). "Interestingly, the present results showed that EGCG, through the modulation of BCL-2, BAX, CASP-3, and CASP-9, prevented pneumonia-induced apoptosis." (PMID 38580929, 2024).
premature ovarian failure (2 papers, 2020 to 2024). "Meanwhile, the expressions of pro-apoptotic markers, which were BAX and CASPASEs (CASPASE-9 and CASPASE-3), were prominently reduced in Esculentoside A-induced premature ovarian failure mice." (PMID 32759462, 2020).
pterygium (2 papers, 2012 to 2023). A wedge-shaped fibrovascular lesion arising from the bulbar conjunctiva and extending to the cornea. "Consistently, the expression of the pro-apoptotic molecule BAX is also increased, supporting the idea of activation of apoptosis in pterygium cells by doxycycline." (PMID 22724003, 2012).
rhabdomyolysis (2 papers, 2018 to 2025). Necrosis or disintegration of skeletal muscle often followed by myoglobinuria. "In our work, the expression of apoptotic genes and the apoptotic index, the ratio of BAX/bcl2, increased in the rhabdomyolysis group." (PMID 40666175, 2025). "Oral usage of RJ (100, 200, and 400 mg/kg) caused a decline in serum CPK, tissue level of total thiols, catalase activity, and renal expression of BAX compared to the rhabdomyolysis group." (PMID 40666175, 2025). "We found that the blockage of HDAC6 by 23BB significantly suppressed BAX/BAK and preserved Bcl-2 in the kidney tissues of rhabdomyolysis-induced AKI." (PMID 29632491, 2018).
rhabdomyosarcoma (2 papers, 2006 to 2022). A rare aggressive malignant mesenchymal neoplasm arising from skeletal muscle.
scrapie (2 papers, 2011 to 2019). A fatal disease of the nervous system in sheep and goats, characterized by pruritus, debility, and locomotor incoordination. "We reported a lack of apoptosis induction despite the significant increase of BAX and BAK in scrapie diencephalons." (PMID 21314976, 2011).
Seizure (2 papers, 2025). A seizure is an intermittent abnormality of nervous system physiology characterized by a transient occurrence of signs and/or symptoms due to abnormal excessive or synchronous neuronal activity in the brain. "Seizures initiate the apoptotic pathway through depleting energy and the accumulation of Ca+ 2 inside the mitochondria, activating both extrinsic (expression of death receptors on the cell surface) and intrinsic factors (mitochondrial dysfunction) that in turn induce BAX release." (PMID 39776284, 2025).
Splenomegaly (2 papers, 2012 to 2024). Abnormal increased size of the spleen. "Additionally, FA downregulated the levels of inflammatory and chemotactic cytokines, alleviated splenomegaly, and exhibited anti-apoptotic effects on KD by reducing TUNEL-positive cells, downregulating BAX expression, and upregulating BCL-2 expression." (PMID 39268468, 2024).
teratoma (2 papers, 2011 to 2022). A non-seminomatous germ cell tumor characterized by the presence of various tissues which correspond to the different germinal layers (endoderm, mesoderm, and ectoderm). "Since several groups have been reported that proapoptotic protein, BAX, expressed frequently in immature teratomas, BAX expression possibly accounts for the induction of apoptosis in PTCH1+/− and PTCH1−/− teratomas." (PMID 35618979, 2022). "Firstly, death of fetal germ cells through a BAX dependent mechanism has been linked to absence of teratomas in C57Bl/6 mice with mutations in teratoma susceptibility genes." (PMID 21674058, 2011).